NRAS (NRAS proto-oncogene, GTPase)
Diseases named in the same sentence as NRAS in open-access papers (continued):
Sharing a sentence is not in itself a finding about the gene and the disease.
melanoma (continued). "In our case report, a young woman with a giant metastasis of NRAS-mutant melanoma in the right hemithorax was immediately operated, however, died few months later due to the development of brain and other distant metastases." (PMID 33100226, 2020). "In an effort to better understand the mechanistic role of FBXO42 in NRAS‐mutant melanoma, we performed a structure–function analysis of FBXO42 when devoid of its functional domains on the activation of the ERK pathway as a readout." (PMID 31549767, 2020). "Although genetic mutations like BRAFV600, NRAS and KIT are crucial in melanoma initiation, progression and metastasis, the pursuit of these targets often disappointed to some proportion of melanoma patients." (PMID 33136551, 2020). "(2019) developed an STK19-targeted small molecule kinase inhibitor and provided evidence that this inhibitor blocks oncogenic, NRAS-driven melanocyte malignant transformation and melanoma growth." (PMID 32531245, 2020). "NRAS+ melanomas are correlated with lower tumor-infiltrating lymphocytes (TIL) grade comparing to wild type, the anatomic site different than scalp or neck, and the presence of higher mitotic index." (PMID 32637031, 2020). "cfDNA was analyzed for BRAF p.V600E, NRAS p.Q61K/p.Q61R, and TERT C228T mutations, as these are frequently found in melanoma patients." (PMID 32486146, 2020). "The loss of the CDKN2A sequence also co-operates with the BRAF and NRAS oncogenes to promote melanoma development." (PMID 33076392, 2020). "The NRAS Q61K mutation is also an oncogenic hotspot (COSM580), and there is promising clinical data in patients with oncogenic NRAS‐mutant melanoma treated with the MEK1/2‐inhibitor, binimetinib." (PMID 32083805, 2020). "For example, following BRAF inhibitor therapy in BRAF V600 mutant melanoma, individual tumors were found to develop multiple resistance events, including NRAS and MEK1 mutations in one patient and two distinct NRAS mutations in another." (PMID 32143590, 2020). "The patients with BRAF K601E (case DM072) and BRAF G466R + NRAS Q61H mutant melanoma (case DM071) progressed after 4 and 7 months, respectively, each with stable disease as best response." (PMID 31839677, 2020). "NRAS-mutant melanomas form thicker tumors and have a higher mitotic rate than NRAS-wildtype melanomas." (PMID 31906480, 2020). "miRNA-204-5p, known as a tumour suppressor gene in melanoma, was associated with the CDKN2A pathway and NRAS gene and contributed to BRAF inhibitor resistance.." (PMID 32993558, 2020). "Common resistance mutations in melanoma are BRAF splice variants, BRAF amplification, neuroblastoma RAS viral oncogene homolog (NRAS) mutations and mitogen-activated protein kinase kinase 1/2 (MEK1/2) mutations." (PMID 33003483, 2020). "Most of the seminal work was done in metastatic malignant melanoma, which is hallmarked by a high prevalence of BRAF (50–60%) and NRAS (15–20%) mutations." (PMID 32046099, 2020). "While in NRAS- or BRAF-mutant melanomas, there are increased levels of KIT promoter hypermethylation." (PMID 32825562, 2020). "For example, in a BRAF-mutant model of melanoma, and NRAS-mutant models of melanoma, breast, and CRC, PGE2 production impairs myeloid cell activation especially the antigen-presenting ability required for T cell activation." (PMID 33092283, 2020). "There was a higher mean MEK 6 gene score in NRAS mutant melanomas compared with NRAS wild-type melanomas (P = 0.023), but the differences were small and there was considerable overlap between the two groups." (PMID 31839677, 2020).
melanoma (continued). "Here, we studied the effect of hypoxia on the EV and cell content of four melanoma cell lines, two carrying a BRAF V600E mutation and two carrying an NRAS mutation, using qPCR arrays (EVs), miRNA microarrays (WCLs) and mass spectrometry." (PMID 32183388, 2020). "Two of the selected studies clearly demonstrated this; the use of THC in mice with induced BRAF/NRAS wild-type tumors promoted autophagy in melanoma cells." (PMID 32839414, 2020). "Only three melanomas from the digits of dogs have been characterised at the genomic level, with two having KRAS mutations and one an NRAS mutation." (PMID 32652526, 2020). "In NRAS mutant melanoma cells, a robust reactivation of the MAPK pathway also occurs within hours in response to MEK inhibition due to loss of negative feedback on CRAF33." (PMID 32504051, 2020). "In high-risk operable or in inoperable stage III and IV melanoma, the most frequently mutated genes are BRAF, NRAS, and c-KIT." (PMID 32054005, 2020). "Put together, our findings reveal a novel mechanism of tumor resistance to MEK inhibition in NRAS‐mutant melanoma, and potentially offering a new therapeutic strategy." (PMID 31549767, 2020). "On that note, an effective combination treatment for NRAS-mutant melanoma remains a therapeutic challenge in this field." (PMID 32042336, 2020). "For example, EGFR/KRAS/ALK in non-small cell lung carcinoma, or BRAF, NRAS in melanoma, in agreement with the ESMO guidelines." (PMID 31787752, 2020). "Our findings further expand the notion showing that pDC density is significantly reduced in NRAS p.Q61-mutated PCM, likely depending on the limited ability of NRAS-mutated melanoma cells to chemoattract pDCs." (PMID 32054102, 2020). "In the example of NRAS melanoma, in addition to identifying the expected Ras‐signalling pathway, we also identified a potential role of cellular cytoskeletal processes, a pathway that is not entirely evident by only exploring individual dependencies." (PMID 33073517, 2020). "Non-CSD melanomas are often associated with BRAFV600E mutations that are found in common nevi as well, while CSD melanomas are often seen to have NF1, NRAS, or BRAFnonV600E mutations." (PMID 33339193, 2020). "As recently reported, potential markers in melanoma are mutations (on BRAF, NRAS, KIT, GNA11/GNAQ, NF1, CDKN2AI, immunohistochemical biomarkers (such as PD-11 and PD-L1, as well as mutated BRAF and NY-ESO-1), miRNAs, and other serum molecules." (PMID 33302400, 2020). "While monotherapy with BRAF inhibitors shows good efficacy against BRAF-mutant melanomas, patients can easily develop resistance through upregulation of RTKs or NRAS." (PMID 32429485, 2020). "These two samples belonged to patients with recurrent metastatic melanomas that have been previously treated with MAPK inhibitors, which is consistent with the notion that NRAS mutation can arise through a resistance mechanism following targeted therapy." (PMID 32784823, 2020). "Most reported MAP2K1 mutations have accompanied other driver mutations of melanoma including BRAF, NRAS, and NF1." (PMID 32483240, 2020). "After the establishment of a definitive diagnosis of a metastatic NRAS-mutant melanoma of occult primary site, the patient was planned to be referred to the Department of Oncology." (PMID 33100226, 2020). "The response rates and duration of responses for targeted therapy in patients with NRAS-mutant melanoma have proven to be modest." (PMID 32825562, 2020). "Depletion of INO80 in the NRAS mutant WM1361 melanoma cell line compromised cellular growth, while RNAse H1 overexpression in the siINO80 WM1361 cells rescued growth by approximately three-fold." (PMID 32913330, 2020). "In order to identify genes essential to maintain sensitivity toward the MEKi trametinib in NRAS‐mutant melanoma, we conducted a whole‐genome CRISPR‐Cas9 knockout screen." (PMID 31549767, 2020).
melanoma (continued). "Cases of melanoma were described in the NRAS‐mutant and one in the double wild‐type group, and although no cases were described in BRAF‐mutant patients this is statistically compatible with the rarity of this genotype." (PMID 31111470, 2020). "In conclusion, these data bring new evidence of the potential tumorigenic role of STAT3 in NRAS-mutant melanomas and will help improving current therapy strategies for this particular patient group." (PMID 31906480, 2020). "Interplay between the CDKN2 proteins and other key drivers of melanoma progression such as BRAF and NRAS mutations must be required for centrosome overduplication." (PMID 32067956, 2020). "Some of these include BRAF amplification, oncogenic NRAS mutations, and MEK1/2 mutations, in addition to a PAX3-mediated upregulation of MITF in approximately 80% of melanoma during early stages of resistance." (PMID 32517051, 2020). "MAPK signaling inhibitor MEK162 abolished the oncogenic roles of FUT8-AS1 silencing in melanoma, which further supports that miR-145-5p/NRAS/MAPK signaling is the critical mediator of the roles of FUT8-AS1 in melanoma." (PMID 34094894, 2020). "The aims of this study were to standardize a highly sensitive methodology of digital PCR (dPCR) to accurately identify hotspot mutations in BRAF, NRAS, and TERT in plasma and interrogate its feasibility as a liquid biopsy tool for melanoma patients." (PMID 33122747, 2020). "In particular, in this study we retrospectively analysed advanced melanomas that had directly progressed from stage IB/II AJCC (American Joint Committee on Cancer) 2017, whose mutational status of BRAF, KRAS, NRAS and PIK3CA genes had already been tested." (PMID 30934988, 2019). "In this study, resistant A375-NRASQ61K (mutant NRAS) and WM983B-BR (wild-type NRAS) melanoma cell lines were used, which harbor BRAFV600E, and exhibit resistance to BRAF inhibitor, Vemurafenib, compared to its parental cells." (PMID 31578454, 2019). "Although, the traditional view has been that a driver oncogenic event typically occur as an activating mutation in protooncogene, such as in NRAS and BRAF genes in case of melanoma." (PMID 31217906, 2019). "In this analysis BRAF, KIT, NRAS, and PIK3CA mutations were examined by next generation sequencing (NGS) in 446 melanomas in a clinical diagnostic setting." (PMID 31277584, 2019). "In summary, we found elevated levels of CDK11 protein expression in both BRAF- and NRAS-mutant melanoma cell lines compared to benign melanocytes." (PMID 30987032, 2019). "In a panel of 49 melanoma-derived cell lines, we sequenced oncogenes that are commonly mutated in melanoma (BRAF, NRAS, KRAS)." (PMID 31253656, 2019). "We also selected the A375 (BRAF mutant) and IPC-298 (NRAS mutant) to validate drug combination predictions for these melanoma subtypes, as they represented cell lines where the full matrix of drug combinations was tested." (PMID 30820351, 2019). "Genetic deletion or pharmacological inhibition of RAC1 in NRAS Q61K-induced melanoma has been shown to suppresses tumor growth, lymph node spread, and tumor cell invasiveness, suggesting a potential value for RAC1 inhibition in this type of tumors." (PMID 31027363, 2019). "We further explored the relationship between the prognostic model and the common BRAF and NRAS mutant in melanoma." (PMID 31649871, 2019). "Loss of CDK11 induces cell cycle dysfunction and death of BRAF- and NRAS-mutant melanoma cell lines." (PMID 30987032, 2019). "In contrast, Akt pathway activation by SC79 increased H3K4me3 and the combination of SC79 and magnolol increased H3K4me3 in both BRAF‐ and NRAS‐mutant melanoma cells (Supplem)." (PMID 30793515, 2019). "In 82% of RAC1P29S/L cases analyzed there was a co-occurring mutation in one of the three main melanoma driver genes BRAF, NRAS, and NF1." (PMID 31257073, 2019).
melanoma (continued). "Mechanistic investigations showed that 2155–14 induces ER stress leading to potentiation of basal autophagy resulting in melanoma cell death in BRAF and NRAS mutated melanoma cells." (PMID 31573152, 2019). "In this sense, in melanoma, the analysis of circulating DNA from tumour has been focused mainly on the detection of driver gene mutations, e.g. BRAF and NRAS." (PMID 30900145, 2019). "Recently, Yin and colleagues reported STK19 can phosphorylate NRAS at Ser-89 and activate oncogenic NRAS to promote melanoma genesis." (PMID 31480283, 2019). "Magnolol, 5,5'‐di‐(tert‐butyl)‐biphenyl‐2,2'‐diol and honokiol were found to be very effective to kill BRAF/NRAS‐mutant melanoma cells at a concentration of 30 μmol L−1 in comparison with 2‐Ome‐3’‐NHAc‐HK and Magreth‐26a‐1‐H." (PMID 30793515, 2019). "Our findings suggest that in visceral metastases of malignant melanoma BRAF- or NRAS-MAFs are rather heterogeneous and cannot be predicted from data of the primary tumor." (PMID 31391014, 2019). "In patients with NRAS-mutant melanoma, a phase III randomized controlled trial assigned either MEK inhibitor, binimetinib, or dacarbazine (DTIC) at a ratio of 2:1 (NEMO)." (PMID 30675668, 2019). "By acutely down-regulating CDK11 protein expression via siRNA transfection, both BRAF- and NRAS-mutant melanoma cells showed significantly reduced cell survival and disrupted cell cycle function." (PMID 30987032, 2019). "Pharmacologic inhibitors of STK19 blocked NRAS phosphorylation and impaired melanoma cell growth and tumor formation capacity, and extended survival of tumor-bearing mice." (PMID 31681559, 2019). "Survival predictions are currently determined on the basis of NRAS/BRAF mutations, even though TERT promoter mutations have been recently associated with a poor prognosis in stage I-II melanomas." (PMID 30934988, 2019). "Among these, activating mutations in BRAF and NRAS gene and inactivating mutations in NF1 gene accounts for over 80% of melanoma and results in the activation of MAP kinase pathway." (PMID 31217906, 2019). "Melanoma cell lines belonging to distinct mutational groups (BRAF-mutant, NRAS-mutant, or wild type for both BRAF and NRAS) co-expressed NFATc2 and EZH2 supporting the rationale for testing the potential anti-tumor effects of pharmacological co-targeting." (PMID 30710146, 2019). "Binimetinib showed an ORR of 20% and a median PFS of 4 months in BRAF-wt NRAS-mutant melanoma patients in a phase II trial." (PMID 30428063, 2019). "To the best of our knowledge, we found for the first time that both BRAF‐ and NRAS‐mutant melanoma cells exposed to magnolol exhibited lower levels of the active histone mark H3K4me3, which presumably will lead to less transcriptional activity." (PMID 30793515, 2019). "While oncogenes have been shown to induce senescence in primary cells, NRAS* and BRAF*-mutated melanoma cells have theoretically negotiated this checkpoint to attain a malignant and immortal state." (PMID 30651601, 2019). "While we also observed a high recall for BRAF, NF1, and TWT drug combination predictions, we found a lower recall (0.29) specifically for the IPC-298 NRAS-mutant melanoma cell line." (PMID 30820351, 2019). "Based on the genomic DNA analysis, melanoma are categorized into four major subtypes that include BRAF-mutant, NRAS-mutant, NF1-deleted/mutated or triple negative melanoma." (PMID 31217906, 2019). "KRAS is often altered in pancreatic carcinoma, colorectal tumors and lung malignancies and HRAS mutations are common in dermatological malignancies and head and neck cancers whereas NRAS alterations in melanomas and in hematopoietic malignancies." (PMID 31681616, 2019). "Recently, new cartridges have been designed to allow the simultaneous detection of the most relevant BRAF and NRAS clinical alterations in a single assay, which is of interest for colorectal tumors and melanoma." (PMID 31415669, 2019).
melanoma (continued). "STK19 activates oncogenic signaling in melanoma cells through selective phosphorylation of mutant NRAS, which supports its interaction with downstream effectors through the RAS binding domain." (PMID 31681559, 2019). "Association of AM404 and GSK126 induced a strong pro-apoptotic effect even in BRAF/NRAS wild-type cell lines and in NRAS-mutant melanomas, compared to treatment with single agents." (PMID 30710146, 2019). "We performed a retrospective analysis of plasma ctDNA using droplet digital PCR (ddPCR) in 30 primary melanoma patients with tumors harboring BRAF, NRAS or TERT promoter mutations." (PMID 30719207, 2019). "The clarification of the contribution of the atypical NRAS and BRAF mutations to mucosal melanoma pathogenesis will however require the development of suitable cellular and animal models for this melanoma subtype." (PMID 31398831, 2019). "Hereditary melanomas have a frequency of NRAS mutations that is double in comparison with sporadic cases, and the NRASQ61 mutation has been observed in 95% of primary melanomas from Swedish patients harboring germline CDKN2A mutations." (PMID 30934534, 2019). "Genetic alterations in the MAPK pathway (including the mutation of KRAS, NRAS and BRAF genes) can cooperate in the development of B16 melanomas and CT26 colorectal carcinoma." (PMID 30935124, 2019). "In drug-naïve BRAFV600 melanoma cells, the RTK expression is low, probably because the strong endogenous BRAF/NRAS mutation-driven activation of the MAPK-ERK signaling pathway selects, against cells with active RTK signaling, to prevent senescence." (PMID 31167513, 2019). "More specifically, 50% of all melanomas harbour BRAF (v-Raf murine sarcoma viral oncogene homolog B) V600 mutations, 15–30% NRAS (neuroblastoma RAS viral oncogene homolog) mutations, whereas NF-1 gene is altered in 12–18% of cases." (PMID 31672982, 2019). "About 50% of melanoma patients harbor activating mutations in BRAF with BRAFV600E as the main protein product, whereas NRAS is mutated in about 15–20% of cases." (PMID 31167513, 2019). "One of the best preserved exclusionary relationships is that between BRAF(V600E) and NRAS(Q61) in melanomas." (PMID 30651601, 2019). "The comparison of CK2α mRNA levels between both NRAS Q61 and G12 mutant melanomas showed a higher expression of CK2α in NRAS Q61 mutant samples, confirming thus the in silico prediction." (PMID 31681616, 2019). "The effects of MAPK suppression on NOXA mRNA were seen in both BRAF and NRAS mutant melanoma cell lines." (PMID 31727958, 2019). "We present the novel finding that down-regulation of CDK11 protein expression reduced cell survival and disrupted cell cycle function in both BRAF- and NRAS-mutant melanomas." (PMID 30987032, 2019). "We determined steady state mRNA expression levels for both CDK11 genes in cultured cells, comparing several BRAF- and NRAS-mutant melanoma cell lines and using adult primary human epidermal melanocytes as a reference control." (PMID 30987032, 2019). "In our study we used ddPCR to investigate the clinical validity of ctDNA measurements in melanoma patients treated with bevacizumab monotherapy by quantifying BRAF, NRAS and TERT promoter mutations in plasma." (PMID 31767937, 2019). "The majority of melanoma patients harboring BRAF and NRAS mutations exhibited the well-known hotspot driver mutations at the V600 (42/44 samples) and Q61 (10/10 samples) loci, respectively." (PMID 30820351, 2019). "A375 is a melanoma cell line, which harbors an activating BRAFV600E mutation while a characteristic NRAS activating mutation exists in Mel JuSo cells." (PMID 31408993, 2019).